ABCB1 (ATP binding cassette subfamily B member 1)
Diseases named in the same sentence as ABCB1 in open-access papers (continued):
Sharing a sentence is not in itself a finding about the gene and the disease.
cancer (continued). "We found that inhibitors of ABCB1 significantly increased the sensitivity of ABCB1 overexpressing cancer cells to BI 2536." (PMID 23593196, 2013). "ABCB1 mRNA levels were significantly lower in dysplastic tissue (P<0.01), morphologically normal tissues 1 and 2 from cancer patients (P<0.01, for both) and tumour tissue (P<0.001) compared to healthy individuals." (PMID 23977225, 2013). "The ATP-dependent transmembrane proteins, P-glycoprotein (P-gp, ABCB1) and multidrug resistance-associated protein 1 (MRP1, ABCC1) are primary contributors to MDR in cancer." (PMID 26082317, 2013). "ABCB1 protein levels were found to be low in CRC tissue compared to well-differentiated tissue in archival material from 51 cancer patients estimated by immunohistochemistry." (PMID 23977225, 2013). "For instance, the primary limitation to efficacy of the antineoplastic drug paclitaxel in drug-resistant cancer cells is the overexpression of the ABCB1 gene." (PMID 23050008, 2012). "The cyclosporine A (CsA) is capable of regulating the efflux function of ABCB1 dependently on its concentration in cancer cells." (PMID 23259070, 2012). "ABCB1 gene promoter presents seven TCF binding sites that have been until now poorly investigated in the regulation of gene transcriptional activity in cancer cells." (PMID 22823957, 2012). "In the present study, we conducted experiments to ascertain the reversal mechanism of vardenafil and tadalafil in ABCB1 overexpressing cancer cells." (PMID 21552528, 2011). "Based on these findings, a number of studies have attempted to selectively inhibit ABCB1 activity as a strategy to reverse MDR in cancer chemotherapy." (PMID 21552528, 2011). "Based on the data presented here, further in vivo studies are warranted to determine if vardenafil can inhibit the ABCB1 transporter and reverse ABCB1-mediated MDR in cancer cells." (PMID 21552528, 2011). "ABCB5 is a member of the ABC protein superfamily, which includes the transporters ABCB1, ABCC1 and ABCG2 responsible for causing drug resistance in cancer patients and also several other transporters that have been linked to human disease." (PMID 21298007, 2011). "Drug-transporting ABC transporters, including ABCB1, were found to be associated with acquired MDR in cancer cells." (PMID 21829205, 2011). "So far, tissue culture studies have consistently shown that the major mechanism of MDR in most cultured cancer cells involves ABCB1(also known as P-glycoprotein, P-gp, or MDR1), ABCC1 (also known as multidrug resistance associated-protein 1, MRP1), or ABCG2." (PMID 20628484, 2010). "This ABC-transporter acts as a drug extrusion pump and mediates the "classical" ABCB1-mediated multidrug resistance (MDR) phenotype of human cancer cells which is characterized by a specific cross resistance pattern." (PMID 20811323, 2010). "Different ABCB1-expressing MDR cancer cells were treated with anti-ABCB1 shRNA expression vector bearing E. coli." (PMID 20811323, 2010). "Cancer stem cells retain the essential property of self-protection through the activity of multiple drug resistance transporters such as ABCB1 (P-glycoprotein) and/or ABCG2 (Breast Cancer Resistance Protein-1, BCRP1)." (PMID 18665178, 2008). "As high ABCB1 surface levels are correlated with an oncogenic phenotype, our data show that Nbeal2 inactivation supports the development of MC neoplasms and probably also other cancer entities." (PMID 41111259, 2026). "Numerous studies have established a strong association between the expression of ABCB1, ATP-binding cassette (ABC) subfamily B member 1, and the development of multidrug resistance in cancer cells acquiring resistance to chemo-therapeutic drugs, including carboplatin and paclitaxel." (PMID 40175339, 2025). "Similarly, elacridar demonstrates activity against both ABCB1 and ABCG2 transporters, rendering cancer cells more susceptible to various anticancer agents." (PMID 39937247, 2025).
cancer (continued). "Variants in ABC transporter genes, including ABCB1, ABCC4, and ABCC3, as well as solute carrier (SLC) genes such as SLC28A3, are known to influence the pharmacokinetics of numerous anti-cancer agents, including fluoropyrimidines, methotrexate, anthracyclines, and irinotecan." (PMID 40428413, 2025). "Overexpression of ABCB1 often leads to multidrug resistance in cancer cells." (PMID 41306963, 2025). "Besides the high potency of erdafitinib against mUC, several recent studies have demonstrated its “off-target” effect in sensitizing cancer cells to certain chemotherapies, due to its ability to interact with ABCB1 and impair its function." (PMID 41154409, 2025). "Likewise, Abcg2-encoding BCRP and Abcb1-encoding ABCB1 are critical transporters at the BBB that restrict the brain permeability to its physiological substrates and anti-cancer drugs in vivo." (PMID 39578077, 2025). "In this work, we first disclosed the widely potent reversing effects of KSQ‐4279, a highly‐selective USP1 inhibitor currently in clinical trial (Phase I) for advanced solid tumors (NCT05240898), on ABCB1/ABCG2/ABCC1‐induced MDR cancers, and the exact mechanisms behind were elucidated." (PMID 41328326, 2025). "ABCB1 overexpression prevents IB‐MECA‐induced cancer cell apoptosis." (PMID 40181576, 2025). "Thus, understanding the upstream regulators of ABCB1 specific to cancer cells is crucial for developing effective and safe treatment strategies." (PMID 40583060, 2025). "ABCB1 (P-gp/P-glycoprotein ABCB1), multidrug resistance-associated proteins (MRPs/ABCC family) and breast cancer resistance protein (BCRP/ABCG2) have been widely implicated in the development of drug resistance across various cancer types." (PMID 40867257, 2025). "Significant decreases in IC50 values of various chemotherapeutic drugs (paclitaxel, vincristine, cisplatin) and enhancements of their intracellular accumulation when used in combination with these TKIs were shown for a broad spectrum of ABCB1-overexpressing cancer cell lines." (PMID 41154409, 2025). "One of the primary mechanisms by which cancer cells acquire multidrug resistance is through the overexpression of ATP-binding cassette (ABC) transporters, such as P-glycoprotein (P-gp/ABCB1), multidrug resistance-associated proteins (MRPs), and breast cancer resistance protein (BCRP/ABCG2)." (PMID 40843170, 2025). "ABCB1 overexpression has been widely reported to confer drug resistance in cancer." (PMID 40427071, 2025). "Interestingly, six genes among these (ABCB1, FGF2, CXCR4, IL6, PSMB9, and CLU), as well as UGCG, are known to be highly associated with cancer resistance to platinum-based chemotherapy." (PMID 40507922, 2025). "Another aim of our investigations was to study the prognostic relevance of P-glycoprotein/ABCB1/MDR1 as a main mechanism for resistance to anthracyclines for the survival time of cancer patients using Kaplan–Meier statistics, evaluating data from the TCGA database." (PMID 40723843, 2025). "Resistance to chemotherapy in cancer cells can arise through various mechanisms, including altered membrane transport through transporters like ABCB1 (MDR1), enhanced DNA repair, defects in apoptotic pathways, and alterations in target molecules, proteins, and cell cycle regulation pathways." (PMID 40216647, 2025). "However, the reduction in MAGMAS levels in these resistant cells led to a noticeable drop in another protein called ABCB1, which helps cancer cells resist drugs." (PMID 40361461, 2025). "Therefore, ABCB1/ABCG2/ABCC1 are recognized as promising targets for the circumvention of MDR in cancer patients." (PMID 41328326, 2025). "P-glycoprotein (P-gp/ABCB1), a key ATP-binding cassette (ABC) transporter, plays a central role in multidrug resistance (MDR), one of the leading causes of chemotherapy failure in cancer treatment." (PMID 40362415, 2025).
cancer (continued). "Despite the complexity of the tumor microenvironment, which requires further confirmation including in vivo study, this work revealed a new approach of combining RN486 with conventional or innovative anticancer drugs for cancer patients diagnosed with overexpressed ABCB1 and ABCG2." (PMID 39081282, 2024). "However, cancers often take advantage of these detoxifying properties of ABCB1 and upregulate its expression in response to chemotherapy." (PMID 39003409, 2024). "These unique metabolites effluxed by ABCB1 in bats may be used to design safer competitive inhibitors of ABCB1 against drug-resistant human cancers, as they are derived from natural metabolites." (PMID 39003409, 2024). "It is speculated that ABCB1 transports anthracyclines extracellularly and reduces their intracellular accumulation, resulting in the resistance of cancer cells and the protection of healthy cells." (PMID 38576421, 2024). "We chose ATP Binding Cassette (ABC) protein B1 (ABCB1, also known as P-glycoprotein) as an example because of its impact on the pharmacokinetics of many drugs, including many cancer treatments, and because many experimental structures exist for its mouse ortholog, Abcb1a." (PMID 39591473, 2024). "Interestingly, previous studies using pancreatic and other cancer cell lines have shown that ABCB1 is involved in gemcitabine resistance." (PMID 38163893, 2024). "ABCB1, an ATP-dependent efflux pump, is a critical factor in resistance to a broad spectrum of chemotherapy drugs, including anthracyclines, taxanes, and Vinca alkaloids, in various cancers (solid and blood-based tumors)." (PMID 39199583, 2024). "Since P-gp efficiently expels doxorubicin from MDR cancer cells, the enhancement of doxorubicin activity in combination with tomoroside A may be due to the inhibition of ABCB1 mRNA expression induced by tomoroside A." (PMID 39339303, 2024). "Notably, there is a strong association between cancer stem cells and the emergence of chemoresistance, and in fact both ABCG2 and ABCB1 are expressed in cancer stem cells." (PMID 38254110, 2024). "ABCB1 knockdown induces the responsiveness of docetaxel-resistant cancer cells toward drug invitro." (PMID 39003454, 2024). "To select a set of miRNAs that could be dysregulated in PDAC and represent possible candidate molecular biomarkers, we decided to focus on one of the most important actors in cancer chemoresistance—MDR1—to identify the miRNAs targeting ABCB1 amplicon." (PMID 38804361, 2024). "Notably, a different study in fact reported increased sensitivity to gemcitabine in a panel of cancer cell lines overexpressing ABCB1, and we find a similar trend in some of our models." (PMID 38163893, 2024). "Additionally, curcumin reduces the expression of the ABCB1 gene and sensitizes resistant cancer cells to vincristine by promoting apoptosis through the activation of caspase-3." (PMID 39339303, 2024). "This interaction might inhibit the efflux of substrates such as DOX, thereby increasing the accumulation of DOX in ABCB1-resistant cancer cells and reversing ABCB1-mediated multidrug resistance." (PMID 38611964, 2024). "Many in vivo and in vitro experiments have revealed that ABCB1 overexpression in particular types of cancer cells significantly decreases the intracellular concentration of paclitaxel by increasing its efflux, which ultimately decreases or abolishes the pharmacological efficacy." (PMID 38228910, 2024). "For this reason, P-glycoprotein, encoded by the ABCB1 gene, may be involved in multidrug resistance phenomena (MDR) in various types of cancer." (PMID 39126083, 2024). "In addition, MDR and, specifically, ABCB1 overexpression, renders cancer cells, including CRPC cells, resistant to PARP inhibitor Olaparib." (PMID 39090086, 2024). "Given the translational relevance of mSWI/SNF ATPase degraders for potential cancer therapeutics, we sought to determine whether ABCB1-dependent resistance mechanisms to PROTAC degraders could be modulated in vivo." (PMID 38557192, 2024).
cancer (continued). "Third, besides cancer therapy, ABCB1 inhibitors could be used for neurodegenerative and psychiatric diseases when the therapeutic drugs are ABCB1 substrates, such as pergolide, bromocriptine, pramipexole, olanzapine, risperidone, and 9-OH risperidone." (PMID 39003409, 2024). "YBX1 has predictive value for drug resistance and poor prognosis in more than 20 cancer types, and upregulates the expression of multiple drug resistance genes, including ABCB1, MVP/LRP, TOP2A, CD44, CD49f, BCL2, and MYC, upon UV irradiation or Cisplatin treatment." (PMID 39168971, 2024). "In summary, our findings illuminate the vulnerability of cancer patients to drug resistance, which is particularly evident in the increased expression of ABCB1 and CYP1B1 in tumor samples from the poor-responders category, along with the associated molecular pathways." (PMID 38534761, 2024). "Alternatively, hemin might serve as a substrate of ABCB1 as doxorubicin, given its role in the effluxion of various cancer substances and drugs." (PMID 39584916, 2024). "ABCB1, a member of the ABC transporters superfamily, plays a crucial role in drug transport and chemo-resistance, often exhibiting overexpression linked to multi-drug-resistant cancers." (PMID 38534761, 2024). "Among the many ABC transporters, subfamily members as P-glycoprotein (shorted as P-gp, encoded by ABCB1 gene), BCRP (referred to the breast cancer resistance protein, encoded by ABCG2 gene) and MRP1 (the multidrug resistance associated protein 1, encoded by ABCC1 gene) are the key triggers of MDR." (PMID 38872211, 2024). "This might re-sensitize cancer cells towards chemotherapeutic drugs, which are originally restricted in use by the activity of ABCB1." (PMID 39580452, 2024). "ABCB1 overexpression is not limited to specific cancer types, and therefore ABCB1 inhibitors could potentially treat a broad range of cancers." (PMID 39003409, 2024). "Our unique approach to the development of ABCB1 inhibitors may help to achieve the long-standing goal of using ABCB1 inhibitors against drug-resistant cancers and other diseases." (PMID 39003409, 2024). "In addition, overexpression of some genes, including ABCB1, TPD52L1, HNRNPR and MICAL3, is associated with poor prognosis in various cancers." (PMID 39682186, 2024). "This counterintuitive observation is known in literature and was attributed to cell-type specific activation of ATP-Binding Cassette (ABC) transporters in cancer cells, e.g., such as overexpression of P-glycoprotein 1 (ABCB1/P-gp), leading to paclitaxel resistance at higher concentrations." (PMID 39696122, 2024). "Among them, ABCB1 was highly expressed in almost all types of MDR cancers, such as adrenocortical, colon, breast, and kidney; and the contribution of ABCB1 to MDR has been proven for many drugs, including vincristine, doxorubicin (DOX), and 5-fluorouracil (5-FU)." (PMID 39114355, 2024). "The upregulation of ATP-binding cassette (ABC) transporters, such as ABCB1 (P-glycoprotein), ABCG2 (breast cancer resistance protein), and ABCC1 (multidrug resistance-associated protein), facilitates the efflux of 5-FU from cancer cells, diminishing its intracellular concentration and efficacy." (PMID 39000577, 2024). "Therefore, administering chemotherapy alongside an ABCB1 inhibitor is an attractive therapeutic approach, particularly for tissues or cancers with high ABCB1 activity." (PMID 39003409, 2024). "Ginsenoside Rg5 could reverse the resistance of the ABCB1-overexpression MDR cancer cells to chemotherapeutic drug docetaxel (TXT) in vitro and in vivo." (PMID 38213735, 2024). "In CRC, m6A‐mediated ABCB1 upregulation conferred doxorubicin resistance to the cancer cells." (PMID 39661414, 2024). "However, cancer cells that acquire high ABCB1 expression through prolonged chemotherapy exposure efflux out chemotherapeutic drugs such as doxorubicin, reducing their efficacy." (PMID 39003409, 2024).
cancer (continued). "Based on tissue distribution and expression in drug-resistant cancer cells, the leading hypothesis was that ABCB1 was involved in the active excretion of toxic xenobiotics and metabolites from the brain and other excretory tissues." (PMID 36973040, 2023). "Additional investigation is required to ascertain the significance of ABCB1 gene level copy number increases and how this might relate to cancer therapy resistance." (PMID 37686513, 2023). "Induction or inhibition of drug transporters such as ABCB1 could potentially alter the pharmacokinetics of anti-cancer agents." (PMID 36707434, 2023). "The ATP-binding cassette subfamily B member 1 (ABCB1), encoding a multidrug transporter referred to as P-glycoprotein (Pgp), plays a critical role in the efflux of xenobiotics in humans and is implicated in cancer resistance to chemotherapy." (PMID 37546821, 2023). "In this study, we investigated the susceptibility of HS-173 to efflux mediated by the multidrug efflux transporters ABCB1 and ABCG2, which are two of the most well-known ATP-binding cassette (ABC) transporters associated with the development of cancer multidrug resistance (MDR)." (PMID 37048130, 2023). "ABCB1/P‐gp (P‐glycoprotein), multidrug resistance‐associated protein 1 (ABCC1/MRP1) and breast cancer resistance protein (ABCG2/BCRP) are the most studied ABC transporters with well‐established roles in mediating multidrug resistance in cancer cell models." (PMID 38102848, 2023). "In addition, ABCB1 inhibitors have been investigated as potential drugs to overcome drug resistance in cancer cells." (PMID 37367074, 2023). "Overexpression of the ABC transporters, ABCB1 and ABCG2, are two of the major mediators of MDR in cancer, and antagonists targeting ABCB1 and ABCG2 have undergone clinical Antagonists targeting ABCB1 and ABCG2 have been clinically evaluated; unfortunately, none have been clinically approved." (PMID 38169723, 2023). "Moreover, polyoxypregnane compounds isolated from MTE have been reported to overcome ABCB1‐ or ABCG2‐mediated multidrug resistance in cancer cells." (PMID 36756719, 2023). "The overexpression of ABCB1 (or P-gp) on cell membranes is an important characteristic of drug-resistant cancer cells; therefore, first-line combination treatments with P-gp inhibitors could delay tumor recurrence." (PMID 37176096, 2023). "Furthermore, MK-2206 did not significantly alter the efficacy of doxorubicin and paclitaxel, which are substrates for the ABCB1 transporter, in the ABCB1-overexpressing cancer cells, KB-C2 and SW620/Ad300." (PMID 37521473, 2023). "Finally, CERS4 knockdown in doxorubicin-resistant MCF-7/ADR cells resulted in reduced activation of cancer-associated pathways (NF-κB, Akt/mTOR, β-catenin, and EMT) and diminished chemoresistance, accompanied by ABCB1 and ABCC1 downregulation." (PMID 37885013, 2023). "While the causes of MDR in cancer are complex and involve multiple factors, it is commonly linked to the overexpression of two well-studied and characterized ATP-binding cassette (ABC) transporters ABCB1 (P-glycoprotein; MDR1) and ABCG2 (BCRP; MXR; ABCP)." (PMID 37762275, 2023). "Advances in elucidating the molecular basis of the MDR phenotype have indicated that elevated membrane expression of drug efflux pumps such as P-glycoprotein (Pgp or ABCB1), multidrug resistance protein 1 (MRP1 or ABCC1), and ABCG2 is a frequent cause of MDR in human cancers." (PMID 37108495, 2023). "A recent review reported that the inhibition of ABCB1 could restore the drug sensitivity of the cancer cells toward chemotherapeutic drugs." (PMID 38023248, 2023). "These three works demonstrate that this mechanism of ABCB1 upregulation may be common among different cancer types and across different chemotherapeutic agents." (PMID 37686513, 2023).